MGLL (monoglyceride lipase)
Description:
Converts monoacylglycerides to free fatty acids and glycerol. Hydrolyzes the endocannabinoid 2-arachidonoylglycerol, and thereby contributes to the regulation of endocannabinoid signaling, nociperception and perception of pain. Regulates the levels of fatty acids that serve as signaling molecules and promote cancer cell migration, invasion and tumor growth.
Synonyms: MGL; MAGL; HU-K5; HUK5
Tractability: Small molecule: a drug acting on it is in phase 2 or 3 trials; a structure with a bound ligand is known; a high-quality ligand is known; it has a high-quality binding pocket; it belongs to a druggable protein family. Antibody: its Gene Ontology location is reachable by antibodies, with high confidence; UniProt places it where antibodies can reach, with medium confidence. PROTAC: ubiquitination databases record sites on it; its protein half-life has been measured; a small molecule that binds it is known.
Target class: Enzyme; Hydrolase
Chemical probes: FAAH/MAGL-IN-5, JJKK-048 (high quality), JNJ-42226314 (high quality), JZP 361
Gene: Protein-coding gene on chromosome 3 (127,689,062 to 128,052,190, reverse strand). Ensembl gene ENSG00000074416.
Subcellular location: Cytoplasm, cytosol; Membrane
Subcellular location (Human Protein Atlas): Vesicles
Pathways (Reactome):
Metabolism: Acyl chain remodeling of DAG and TAG; Triglyceride catabolism
Gene expression (Transcription): MLL4 and MLL3 complexes regulate expression of PPARG target genes in adipogenesis and hepatic steatosis
Hemostasis: Arachidonate production from DAG
Gene Ontology:
Molecular function: monoacylglycerol lipase activity; protein binding; protein homodimerization activity; phosphatidylcholine lysophospholipase activity
Biological process: acylglycerol catabolic process; arachidonate metabolic process; inflammatory response; lipid metabolic process; monoacylglycerol catabolic process; regulation of endocannabinoid signaling pathway; regulation of inflammatory response; regulation of sensory perception of pain; regulation of signal transduction; triglyceride catabolic process
Cellular component: cytosol; endoplasmic reticulum membrane; membrane; plasma membrane
Genetic constraint (gnomAD): Loss-of-function variants: 9 observed, 31.39 expected, observed/expected ratio (o/e) 0.29, 90% interval 0.17 to 0.5. The upper end of that interval is the gene's LOEUF score, 0.5, which puts it in group 2 of 6, group 1 being the genes least tolerant of losing a copy. Missense variants: 356 observed, 421.28 expected, observed/expected ratio (o/e) 0.85, 90% interval 0.77 to 0.92. Synonymous variants: 148 observed, 170.7 expected, observed/expected ratio (o/e) 0.87, 90% interval 0.76 to 0.99.
Homologues: Orthologues: chimpanzee MGLL (100% identical), macaque MGLL (94% identical), dog MGLL (89% identical), pig MGLL (88% identical), rat Mgll (83% identical), mouse Mgll (81% identical), guinea pig MGLL (68% identical), tropical clawed frog mgll (60% identical), zebrafish mgll (54% identical).
Diseases named in the same sentence as MGLL in open-access papers:
MGLL is named in the same sentence as 168 diseases in open-access papers, as found by Europe PMC text mining. Sharing a sentence is not in itself a finding about the gene and the disease. The quoted sentences say what the papers report.
prostate carcinoma (21 papers, 2010 to 2024). A carcinoma that arises from epithelial cells of the prostate gland. "As revealed in the datasets of cancer genomic projects, MGLL amplification is common in various tumor types such as prostatic carcinomas with neuroendocrine phenotypes and pancreatic ductal adenocarcinomas." (PMID 27366945, 2016). "Our recent studies have indicated that KLF4 upregulates MGLL and BIK in HCC and prostate cancer cells." (PMID 30658712, 2019).
breast cancer (18 papers, 2015 to 2025). A primary or metastatic malignant neoplasm involving the breast. "This contrasts with our findings below that decreased MGLL mRNA levels are associated with worse prognosis in breast cancer." (PMID 39351361, 2024). "Deficiency of MGLL (monoacylglycerol lipase) is involved in oral carcinoma, metastatic hepatocellular carcinoma, breast cancer, and GIST." (PMID 35178443, 2022). "MGLL is a key hub in the lipid signaling network and has been found to be involved in the development of varieties of tumor, such as breast cancer and melanoma cancer." (PMID 36550099, 2022).
colorectal cancer (18 papers, 2016 to 2023). A primary or metastatic malignant neoplasm that affects the colon or rectum. "Deficiency of MGLL is also associated with colorectal cancer progression along with other genes by regulating ECM and metabolism." (PMID 35178443, 2022). "A deficiency in monoacylglycerol lipase (MGLL) can cause lipid accumulation in TAMs of colorectal cancer, resulting in M2 macrophage activation and inhibiting CD8+ T cell function." (PMID 35884391, 2022). "MGLL expression was significantly reduced in the majority of primary human lung cancers and primary colorectal cancers compared to normal tissues." (PMID 32998690, 2020). "MGLL upregulation has been reported in several tumor tissues, including hepatocellular carcinoma and colorectal cancer." (PMID 33363004, 2020). "detected reduced MGLL expression in colorectal cancer tissues and reported a tumor suppressive effect for MGLL overexpression in colon cancer cells." (PMID 33363004, 2020). "Colorectal cancer‐associated TAMs have an increase of abhydrolase domain containing 5 (ABHD5), the cofactor of adipose triglyceride lipase, and a decrease of monoacylglycerol lipase (MGLL)." (PMID 34766109, 2020). "The role of MGLL in colorectal cancer oncogenesis, however, is controversial." (PMID 33363004, 2020). "Notably, contradictory results regarding the oncogenic versus tumor suppressive functions of MGLL have been reported for the same tumor type, such as colorectal cancers." (PMID 27366945, 2016). "We performed immunohistochemical staining in specimens from patients with colorectal cancer (CRC) and found that MGLL expression in macrophages in carcinoma tissues was much lower than that in adjacent normal tissues." (PMID 29968710, 2018).
Obesity (18 papers, 2010 to 2025). Accumulation of substantial excess body fat. "We identified 30 studies that included association between a FAAH or MGLL gene variant and any obesity-related outcome in a human sample." (PMID 34959715, 2021). "Three studies used bioinformatic approaches to identify novel genetic variants in FAAH and MGLL genes associated with obesity or obesity-related traits." (PMID 34959715, 2021). "While our review considered only candidate gene association studies in humans involving FAAH or MGLL, a brief note on genome-wide association studies (GWAS) of obesity is worthwhile." (PMID 34959715, 2021). "In this study, we generated high quality sequencing data to analyze the association of DNA variants in two candidate genes, FAAH and MGLL, with extreme obesity." (PMID 21118518, 2010). "The expression of FAAH and MGLL in numerous tissues will make it challenging to determine the exact role that the regulatory variants identified in our study play in obesity." (PMID 21118518, 2010). "In this report, we explore the genetic diversity of 188 kb of sequence encompassing the FAAH and MGLL genes in 289 individuals and use variants from the whole allelic frequency spectrum to investigate association with extreme obesity (BMI ≥40 kg/m2)." (PMID 21118518, 2010). "Thus, FAAH and MGLL are excellent candidates to be sequenced in the extreme of the BMI distribution to find the extent of their genetic diversity and potential association of variants with obesity." (PMID 21118518, 2010). "The main objective of this study was to determine if MGLL modulates the gut microbiome of mice and its response to a HFD in order to gain an understanding of the mechanisms by which Mgll−/− mice are resistant to diet induced obesity and related metabolic perturbations." (PMID 33348740, 2020). "Since the relatively common FAAH P129T mutation has been associated with obesity in some studies, it is possible that other rare FAAH variants or MGLL variants may also contribute to ECS tonic activation in severely obese individuals." (PMID 20098695, 2010). "Our application of the method on the CRESCENDO individuals, generates plausible hypotheses on the role of FAAH and MGLL in of obesity." (PMID 20976246, 2010). "Given that augmented fatty acid release in the basal condition caused by increased lipolytic enzymes is implicated in the development of insulin resistance of adipocytes, up-regulation of MGLL in CP rats may contribute to the pathogenesis or progression of obesity related to the metabolic syndrome." (PMID 24468282, 2014). "Accordingly, PLA2G2A and PLA2G4A genes were up-regulated by omega-3 polyunsaturated fatty acids supplementation, whereas SLC27A2, CNR1, DAGLA, MGLL, FAAH, SLC27A1, and SLC27A2 genes were found to be down-regulated in people living with healthy obesity." (PMID 38024342, 2023). "scWAT gene expression of SLC27A2, CNR1, DAGLA, MGLL, FAAH, SLC27A1 and SLC27A2 were lower in individuals living with healthy obesity." (PMID 38024342, 2023). "A review of these data found no SNPs in FAAH, MGLL, or DAGLA/DAGLB that showed genome-wide significant association (p < 5 × 10−8) with obesity or related outcomes (no SNPs in CNR1 either)." (PMID 34959715, 2021).
hepatocellular carcinoma (15 papers, 2016 to 2025). A malignant tumor that arises from hepatocytes. "For instance, MGLL was reported as a potential tumor suppressor in hepatocellular carcinomas, associated with its loss of protein expression, which was posttranslationally dictated by SND1-promoted ubiquitination for proteasome-mediated proteolysis." (PMID 27366945, 2016). "We also measured the expression levels of the epithelial-to-mesenchymal transition (EMT) markers E-cadherin and N-cadherin, which were reported to be regulated by MGLL in hepatocellular carcinoma." (PMID 33363004, 2020). "In hepatocellular carcinoma, for example, MGLL promotes disease progression via NF-kB-mediated EMT transition." (PMID 33363004, 2020). "The functional significance of MGLL has been documented in various malignancies, including endometrial adenocarcinoma, lung adenocarcinoma, non small cell lung cancer, melanoma, hepatocellular carcinoma, and colon cancer." (PMID 40994935, 2025).
melanoma (15 papers, 2016 to 2025). A malignant, usually aggressive tumor composed of atypical, neoplastic melanocytes. "Additionally, MGLL has been reported to play a role in melanoma." (PMID 37033945, 2023).
colon carcinoma (13 papers, 2018 to 2025). "With primary investigation in colon cancer and confirmation in other cancer models, here we determine that deficiency of monoacylglycerol lipase (MGLL) results in lipid overload in TAMs." (PMID 29968710, 2018). "MGLL is characterized as a direct PRDM5 target in human colon cancer cells and in Prdm5 mutant mouse intestines." (PMID 35178443, 2022). "Box plots showing log2 transformed and median normalized values for (a) FASN (b) HMGCR (c) MGLL expression levels in KCL22 (Leukemia), KG1 (Leukemia), KU812 (Leukemia), SW480 (Colon cancer), SW620 (Colon cancer) and A549 (Lung Cancer)." (PMID 31138183, 2019).
lung carcinoma (10 papers, 2020 to 2024). "In lung cancer, the upregulation of MGLL was found to accelerate tumor progression and metastases, and resultantly, lead to a poor prognosis." (PMID 39682235, 2024). "Here, our data indicate that MGLL can promote lung cancer cell metastasis, both in vitro and in vivo." (PMID 33363004, 2020). "Taken together, our results suggest that enhanced MGLL expression promotes lung cancer cell proliferation and tumor growth in vitro and in vivo." (PMID 33363004, 2020). "In lung cancer, MGLL inhibition led to a decrease in cell proliferation, invasion, and metastasis." (PMID 37033945, 2023). "However, the role of MGLL in lung cancer has not been elucidated." (PMID 33363004, 2020).
glioblastoma (6 papers, 2020 to 2024). The most malignant astrocytic tumor (WHO grade IV). "In glioblastoma, tumor cells can activate MGLL through ARS2, and monoacylglycerol lipase (MAGL) is the translation product of MGLL, which can produce PGE2 to promote M2 polarization." (PMID 36387147, 2022).
pancreatic cancer (6 papers, 2021 to 2025). "Monoacylglycerol lipase (MGLL), an important enzyme catabolizing lipid that extensively exists in pancreatic cancer cells, plays an important role in triacylglycerol (TG) metabolism." (PMID 35992338, 2022). "The MGLL gene is highly expressed in pancreatic cancer compared to the normal pancreas." (PMID 40075699, 2025). "Another study did not associate MGLL protein expression in nerves with pain levels in pancreatic cancer; however, this study did not evaluate whether the expression of MGLL in cancer cells could be associated with pain experienced by patients." (PMID 40075699, 2025).
glioma (5 papers, 2020 to 2022). A benign or malignant brain and spinal cord tumor that arises from glial cells (astrocytes, oligodendrocytes, ependymal cells). "Our findings indicate that ARS2 expression is correlated with poor prognosis of glioma patients and, importantly, promotes the tumorigenicity of GSCs through direct transcriptional induction of MGLL in the brain." (PMID 32532977, 2020).
Hypertension (5 papers, 2020 to 2025). The presence of chronic increased pressure in the systemic arterial system. "This study provides novel evidence that TZ, an α1-adrenergic receptor antagonist primarily employed in the treatment of BPH and hypertension, alleviates age-related endothelial dysfunction by inhibiting MGLL-mediated PA accumulation." (PMID 40972970, 2025).
Insulin resistance (5 papers, 2011 to 2025). Increased resistance towards insulin, that is, diminished effectiveness of insulin in reducing blood glucose levels. "Concurrently, recent investigations have identified acetyl-11-keto-β-boswellic acid (AKBA) as another potent MGLL inhibitor, demonstrating therapeutic potential in addressing non-alcoholic fatty liver disease and its associated metabolic complications, including weight gain and insulin resistance." (PMID 40994935, 2025). "A previous study showed that whole-body MGLL knockout mice exhibited decreased forskolin-stimulated fatty acid and glycerol release from white adipose tissues and attenuated high-fat diet-induced insulin resistance." (PMID 24468282, 2014).
lung adenocarcinoma (5 papers, 2018 to 2025). A carcinoma that arises from the lung and is characterized by the presence of malignant glandular epithelial cells. "In this study, we aimed to characterize the role of MGLL in the development of lung adenocarcinoma (LUAD)." (PMID 33363004, 2020).
osteoarthritis (5 papers, 2016 to 2025). A noninflammatory degenerative joint disease occurring chiefly in older persons, characterized by degeneration of the articular cartilage, hypertrophy of bone at the margins and changes in the synovial membrane. "MGLL inhibitors have been evaluated in models of osteoarthritis, bone cancer pain and neuropathic pain, including pain induced by chemotherapeutic drugs." (PMID 40075699, 2025).
endometrial adenocarcinoma (3 papers, 2022 to 2025). "Emerging evidence demonstrates that ABX-1431, a novel MGLL inhibitor, effectively reverses progesterone resistance and enhances progesterone sensitivity in endometrial adenocarcinoma." (PMID 40994935, 2025). "Inhibitors targeting MGLL hold promise in treating progesterone-resistant endometrial adenocarcinoma." (PMID 38660376, 2024). "The overexpression of MGLL is key in endometrial adenocarcinoma onset and progression, and resistance to progesterone." (PMID 38660376, 2024). "In conclusion, the high expression of MGLL is involved in the occurrence and development of endometrial adenocarcinoma and progesterone resistance." (PMID 36550099, 2022). "In this study, we first found MGLL was highly expressed in progesterone resistant samples of endometrial adenocarcinoma, and then we verified its expression was increased in endometrial adenocarcinoma." (PMID 36550099, 2022). "MGLL, an important factor involved in lipid mobilization, is overexpressed in many tumors, however the biological function of MGLL in the development of endometrial adenocarcinoma and the process of progesterone resistance still remains unclear." (PMID 36550099, 2022). "In addition, knockdown of MGLL can sensitize endometrial adenocarcinoma cells to progesterone, possibly by affecting ROS generation and reducing the expression of AKR1C1." (PMID 36550099, 2022).
gastrointestinal stromal tumor (3 papers, 2016 to 2024). "MGLL, as a lipid metabolic enzyme, is directly linked to the progression of gastrointestinal stromal tumors due to its correlation with adverse clinicopathological." (PMID 38660376, 2024). "In gastrointestinal stromal tumors (GISTs), overexpression of monoglyceride lipase (MGLL) is correlated with adverse clinicopathological factors, suggesting a pathogenic role in the aggressive phenotype of primary localized gastrointestinal stromal tumors." (PMID 35785165, 2022). "In brief, MGLL is a lipid-metabolizing enzyme correlated with the progression of gastrointestinal stromal tumors with adverse clinicopathologic factors and independent adverse prognostic effects." (PMID 35785165, 2022). "MGLL mRNA levels were significantly increased from adjacent normal tissues to non-high-risk groups, and gastrointestinal stromal tumors were significantly elevated and correlated with immune expression levels from non-high-risk to high-risk groups." (PMID 35785165, 2022).
lung squamous cell carcinoma (3 papers, 2020 to 2025). "However, in this study, we did not investigate the roles of MGLL in lung squamous cell carcinoma (LUSC), which is another broad subtype of non-small cell lung cancer." (PMID 33363004, 2020).
Sepsis (3 papers, 2023 to 2026). Sepsis is defined as life-threatening organ dysfunction caused by a dysregulated host response to infection. "We identified significant upregulation of NTSR1, BCL6, ZDHHC19, MGLL, and ALPK1 in sepsis compared to healthy individuals, while VAV2 and SATB1 were significantly downregulated in sepsis." (PMID 38167131, 2024). "The observed significant upregulation of NTSR1, BCL6, ZDHHC19, MGLL, and ALPK1 in sepsis compared to healthy individuals, along with the notable downregulation of VAV2 and SATB1 in sepsis, provides a comprehensive picture of the altered gene expression landscape during sepsis." (PMID 38167131, 2024). "Additionally, bulk RNA analysis revealed significant increases in NTSR1, BCL6, ZDHHC19, MGLL, and ALPK1 in sepsis, and significant decreases in VAV2 and SATB1 in sepsis; FCHO1 showed a significant decrease in sepsis patients who did not survive compared to those who survived at 28 days." (PMID 38167131, 2024).
triple-negative breast carcinoma (3 papers, 2022 to 2024). An invasive breast carcinoma which is negative for expression of estrogen receptor (ER), progesterone receptor (PR), and human epidermal growth factor receptor 2 (HER2). "Inhibition of MGLL (monoacylglycerol lipase), which is an enzyme involved in the generation of fatty acids and glycerophospholipids from monoacylglycerol, was associated with decreased infiltration into the blood–brain barrier in triple-negative breast cancer in mouse models." (PMID 39351361, 2024).
COVID-19 (2 papers, 2021 to 2023). A disease caused by infection with severe acute respiratory syndrome coronavirus 2. "Nonetheless, we detected an increase in the gene expression of MGLL, which is orthologous to monoacylglycerol lipase (MAGL) in COVID-19 patients receiving GCs, indicating higher 2-AG breakdown by MAGL to glycerol and AA synthesis." (PMID 36851787, 2023).
diabetes (2 papers, 2020 to 2024). "Given what is known about MGLL function, it could be a potentially interesting target for the controlling of adipogenesis and has implications to insulin sensitivity in diabetes." (PMID 39595019, 2024).